ENSG00000276105
Gene: Miscellaneous RNA gene on chromosome 11 (2,674,097 to 2,674,292, forward strand). Ensembl gene ENSG00000276105.
Gene Ontology:
Cellular component: nucleolus